CGAS (cyclic GMP-AMP synthase)
Diseases named in the same sentence as CGAS in open-access papers (continued):
Sharing a sentence is not in itself a finding about the gene and the disease.
viral infection (continued). "Based on our results, we conclude that viral infection induces the association of ZCCHC3 and cGAS, which have a high affinity to viral dsDNA, leading to cGAS activation and induction of downstream effector genes." (PMID 30135424, 2018). "Here, the authors identify a zinc finger protein, ZCCHC3, that enhances the binding of cGAS to dsDNA and is important for its activation following viral infection." (PMID 30135424, 2018). "Systemic study on these dynamic processes of PTMs in vivo during virus infection will provide more exciting and convincing insights into cGAS-mediated signaling." (PMID 29546673, 2018). "ZCCHC3 directly binds to dsDNA, enhances the binding of cGAS to dsDNA, and is important for cGAS activation following viral infection." (PMID 30135424, 2018). "After viral infection, viral nucleic acids are sensed by PRRs, including RLRs and cGAS, thereby initiating the activation of type I IFN production pathways." (PMID 30018336, 2018). "At the same time, viral infection (such as herpesviruses) imposes cellular stress that triggers mitochondrial DNA damage and release to activate cGAS-STING pathway." (PMID 29202128, 2017). "During viral infections, Akt becomes activated and phosphorylates the enzymatic domain of cGAS on Ser291 (for mouse) and Ser305 (for human)." (PMID 27696330, 2016). "cGAS knockout mice abolish the ability to initiate type I IFN production when administrated with cytosolic DNAs either through transfection or viral infection." (PMID 27696330, 2016). "Taken together, these data suggest that the cGAS–STING signalling pathway is required for neutrophil NET DNA-induced M1 macrophage differentiation during virus infection, and we further hypothesized that Piezo1 plays a regulatory role in antiviral immunity." (PMID 39890818, 2025). "Since cGAS functions as a cytosolic DNA sensor upon viral infection, we next investigated whether Rep protein also localizes in the cytoplasm." (PMID 40523029, 2025). "Early in viral infection, after the formation of cGAS-DNA condensates, ORF52/VP22 accumulates in cGAS-dsDNA condensates and replaces cGAS-DNA condensates as viral envelope proteins and DNA form condensates through multivalent interactions of positive and negative charges." (PMID 39757214, 2025). "In addition, the HDAC6 ∆NLS mutant apparently reduced the binding of cGAS to viral DNA and promoted viral infection." (PMID 39747662, 2025). "Together, these results suggest that IRF4 plays a role in subverting multiple immune surveillance mechanisms by the transcriptional control of related genes, including PD-L1 and PD1, and cGAS and STING, in the context of oncogenic viral infection that is associated with blood cancers." (PMID 40733503, 2025). "Consequently, our data suggest that macrophage‐derived vesicles function as adjuvants, leveraging the cGAS‐STING pathway to augment immune responses against viral infections." (PMID 39513669, 2025). "Moderate inflammation elicited by PAMPs could be beneficial for safe elimination of viral infection due to controlled activation of type I interferon markers; for example, by the cGAS-STING pathway, and elicitation of IFN-α and IFN-β." (PMID 40977838, 2025). "cGAS-STING pathway has been reported to play crucial roles in virus infection." (PMID 41158134, 2025). "In addition, we show that BTV infection blocks DNA-induced IFN-I transcription and that virus infection prevents DNA sensing by inducing cGAS and STING degradation." (PMID 39836220, 2025). "This evidence shows that cGAS-STING plays a key role in host resistance to viral infection." (PMID 38426093, 2024). "cGAS-STING-mediated autophagy plays a dual role during viral infection." (PMID 38426093, 2024). "Upon viral infection, the ISG tripartite motif 14 (TRIM14) directly binds to the C-terminus of cGAS and recruits ubiquitin-specific peptidase 14 (USP14) to prevent K48-linked ubiquitination and degradation of cGAS." (PMID 38660307, 2024).
viral infection (continued). "However, the processes controlling cGAS stability, particularly feedback regulation during viral infections, remain unclarified." (PMID 39183465, 2024). "Therefore, the cGAS-STING pathway is considered an evolutionary conserved defense mechanism against viral infections." (PMID 38848144, 2024). "In mice peritoneal macrophages, viral infection triggers the activation of the UAF1-USP1 deubiquitinase complex, which specifically combines with cGAS to cleave its K48-linked polyubiquitination, enhancing its protein level and cGAS-dependent type I IFN responses." (PMID 39183465, 2024). "The cGAS-STING pathway has a crucial function in the innate immune response to viral infections." (PMID 38720392, 2024). "Currently, there are few studies on the interaction between cGAS-STING and inflammasome signalling in viral infection, but the available evidence already suggests that the interplay between the cGAS-STING pathway and inflammasome complex affects IFN, inflammation and cell death." (PMID 38426093, 2024). "Whether TRIM5α synergizes with cGAS to restrict virus infection and induce innate activation remains to be tested." (PMID 39431915, 2024). "Additionally, virus infection can trigger the expression of Casp3; therefore, Casp3 cleavage of cGAS and IRF3 can be used as an immune evasion mechanism." (PMID 38675916, 2024). "In addition to autoimmune diseases, tumors, and viral infections, a variety of Chinese herbal medicines can ameliorate other diseases by impacting the cGAS-STING pathway, potentially in conjunction with other molecular targets." (PMID 39737190, 2024). "Tumor derived ISG expression could stem from response to exogenous interferon or cytosolic nucleic acid sensing due to viral infection or genomic instability, the latter resulting in chronic cGAS-STING pathway activation." (PMID 38355954, 2024). "It has been found that cGAS-STING pathway can recognize a variety of cytosolic double-stranded DNA (dsDNA), contributing to cause a robust type I interferon response thereby affecting the occurrence and progression of viral infection." (PMID 38693578, 2024). "Further functional studies revealed that the activated cGAS phosphorylates its downstream effector protein STING at the Ser365 position upon viral infection and subsequently promotes type I IFN production and ISGs expression via TBK1-IRF3 and JAK-STAT pathways." (PMID 38426093, 2024). "The liver and gut are the major sites of interferon-stimulated gene (ISG) expression during viral infection in fish; therefore, cGAS may play an important role in antiviral innate immunity in fish." (PMID 36845102, 2023). "We observed that cGAS protein levels were lower at six hours after WT VACV infection in BMDCs compared with mock-infection control, suggesting that cGAS protein might be degraded after viral infection." (PMID 37217469, 2023). "The cGAS-STING signaling pathway inhibits a variety of viral infections." (PMID 37600809, 2023). "To explore the function of cGAS in response to viral infections, we infected the cGAS-KO DEF cells (cGAS-/-) and the normal control DEFs (cells transfected with empty vector pX459-v2, EV) with DAdV B2, SBDSV and NDRV viral strains at the MOI of 0.25 and harvested at the indicated time points." (PMID 36733488, 2023). "In summary, this is the first study to explore the role of du-cGAS in response to viral infections." (PMID 36733488, 2023). "Generally, these results reveal that du-cGAS is a vital component of the innate immune system of ducks, with a universal antiviral activity, and provides a useful strategy for the control of waterfowl viral diseases." (PMID 36733488, 2023). "Recent extensive studies have shown that mtDNA is released under pathological conditions, such as oxidative stress, genotoxic stress, high levels of proinflammatory factors, viral infection, and mitochondrial dysfunction, subsequently activating the cGAS-STING pathway." (PMID 36964253, 2023).
viral infection (continued). "Although the functions of mammalian and chicken cGAS have been extensively studied, the function of du-cGAS in response to duck-origin virus infection remains unclear." (PMID 36733488, 2023). "Finally, the human heart samples were not analyzed for the presence of viral DNA or RNA, reflective of viral infection, which is known to activate the CGAS-STING1 pathway." (PMID 37577061, 2023). "During virus infection, Mn2+ is released from membrane wrapped organelles and then accumulated into cytosol, which can further directly binds to cGAS in the cytosol, promoting the binding of cGAS and dsDNA to activate cGAS." (PMID 37153576, 2023). "Perturbations of mRNA translations such as frameshifts are quite common during viral infections; indeed, a recent discovery describes activation of cGAS by pure ribosomes, and this activation may be reminiscent of ribosome collision in vivo." (PMID 38139802, 2023). "Besides cytosol dsDNA, cytoplasmic manganese (Mn2+) released from membrane-enclosed organelle binds to cGAS to enhance the sensitivity of cGAS to dsDNA by several orders of magnitude upon viral infection." (PMID 35803579, 2022). "However, current therapeutic research for viral infections has concentrated on the use of broad-spectrum therapeutic approaches that activate cGAS/STING signaling." (PMID 36189363, 2022). "More interestingly, acyclovir blocked viral infection-induced nuclear soluble cGAS." (PMID 35538147, 2022). "Thus, the activation of cGAS/STING signaling plays a more detrimental role in the severe inflammatory response at the late stage of a viral infection than the beneficial effect of limiting viral replication." (PMID 36189363, 2022). "Moreover, the activated caspase-3 can cleave cGAS, mitochondrial antiviral signaling protein (MAVS), and IRF3 to prevent the production of IFN-I during virus infection-caused apoptosis." (PMID 36189363, 2022). "In agreement with the fact that DNA sensing by cGAS needs to be inhibited immediately upon release of the viral genome, inhibition of cGAS activation occurs very early during viral infection and is mediated by ORF52 proteins introduced with the invading virion." (PMID 36231111, 2022). "Given that PCBP2 associates with cGAS and that this association is regulated by viral infection, we reasoned that PCBP2 might regulate cGAS-STING-mediated antiviral signaling by targeting cGAS." (PMID 35322803, 2022). "Although it is currently unknown whether there exist additional ISGylated targets of ARIH1 in the context of viral infection, the available data have suggested a positive feedback loop of cGAS ISGylation by ARIH1 to promote antiviral immunity." (PMID 36217001, 2022). "Among them, cGAS-STING alerts on the presence of both exogenous and endogenous DNA in the cytoplasm, and this pathway has been closely linked to multiple diseases, including auto-inflammation, virus infection, and cancer." (PMID 35979145, 2022). "For example, cGAS is found to be unphosphorylated at the resting state to restrain its inappropriate activation by associating with PPP6C, and this interaction is alleviated upon viral infection, allowing for cGAS phosphorylation that primes cGAS activation." (PMID 35795661, 2022). "Recently, researchers found that manganese (Mn), a transition metal, is released from membrane-enclosed organelles upon viral infection and directly bounds to cGAS, which increases the sensitivity of the cGAS-STING pathway for double-stranded DNA (dsDNA) to produce type I IFNs." (PMID 35292881, 2022). "Next, we asked whether ORF9 expressed from its endogenous promoter during viral infection had the ability to interact with cGAS." (PMID 35670106, 2022). "Furthermore, cGAS is constitutively associated with the PP6 catalytic subunit (PPP6C) in resting cells, and dissociation of PPP6C occurs upon virus infection." (PMID 36591232, 2022).
viral infection (continued). "However, their study relied on a constitutively active cGAS/STING overexpression system outside the context of virus infection." (PMID 35022513, 2022). "The activation of the cGAS-STING pathway may be beneficial during viral infections and potentiate the anti-viral activity of immune cells or result in pathological consequences in conditions, such as autoimmune diseases." (PMID 36230930, 2022). "We next assessed the expression of proteins associated with cGAS-STING signaling, a cytosolic DNA sensing pathway involved in initiating a type-I interferon response to genotoxic stress or viral infection which has been shown to be elevated in brain injury and neurodegenerative diseases." (PMID 36408415, 2022). "cGAS-STING pathway has been crucially implicated in autoimmune diseases, cellular senescence, and cancer immunotherapy, while the cGAS-like receptors in bacteria can protect it against viral infections." (PMID 36619988, 2022). "Therefore, targeting these factors to reactivate cGAS/STING signaling for specific viral infections is a novel viral therapy strategy." (PMID 36189363, 2022). "It raises the question of an unknown ligand or crosstalk of signaling pathways that triggers the activation of cGAS to establish a basal antiviral state in the cells, with the ability to control virus infection." (PMID 33708225, 2021). "The activity of cGAS is essential for the detection of CDNs by STING in viral infection." (PMID 33858455, 2021). "While initially recognized for its critical function in the innate immune response against viral infections, recent studies indicate that cGAS/STING-IFN-I pathway also mediates many other stress responses including signaling from DNA damage and oxidative stress." (PMID 33510167, 2021). "However, our data now raise the exciting possibility that cGAS directly senses the dramatic subversion of host-cell protein production occurring during virus infection." (PMID 34111399, 2021). "While activation of the cGAS/STING pathway has been shown to limit viral replication during CNS viral infection, chronic and dysregulated activation may be detrimental." (PMID 34504493, 2021). "Disruption of cGAS/STING signaling enhances susceptibility to bacterial and viral infection." (PMID 34504493, 2021). "The cGAS–STING pathway is primarily activated by dsDNA that enters the cytoplasm abnormally; therefore, it is tempting to emphasize the connection between the cGAS–STING pathway and viral infections, such as those caused by classical herpes simplex virus type 1." (PMID 34906241, 2021). "The cGAS-STING pathway has been identified to protect the host against viral infection." (PMID 35095914, 2021). "During viral infection, stresses placed upon cells can lead to the release of DNA into the cytoplasm of infected cells, thus leading to the activation of cytosolic DNA sensors, such as cGAS." (PMID 33057424, 2020). "Considering the important role of the ER-localized STING in anti-viral innate immunity, we speculate that ER-phagy may be involved in the inhibition of the cGAS-STING pathway during virus infections, particularly DNA virus infection." (PMID 32456258, 2020). "Furthermore, TRIM38 mediates cGAS SUMOylation in uninfected cells and during the early phase of viral infection, which promotes cGAS protein stability by preventing cGAS from K48-linked polyubiquitination and degradation." (PMID 33105828, 2020). "The detection of cytosolic DNA by cGAS is the major input of the STING pathway in viral infection." (PMID 32532954, 2020). "The activation of the cGAS-STING pathway is currently believed to be as follows: DNA present in the cytosol (e.g. due to viral infection) is recognised by cyclic GMP-AMP synthase (cGAS), which produces cyclic GMP-AMP (cGAMP) that can activate Stimulator of Interferon genes (STING)." (PMID 31114634, 2019).
viral infection (continued). "Viral infection of the host can trigger innate immune responses, and previous studies have revealed that cyclic GMP-AMP synthase (cGAS)/STING and RIG-I/MAVS pathways play important roles in host innate immunity against HPV-induced precursor lesions and invasive cancer of the uterine cervix." (PMID 31803230, 2019). "Armenia/07-induced blockage of the cGAS-STING pathway happens early during viral infection." (PMID 30918080, 2019). "Finally, because untethering alone is sufficient to activate cGAS without the need for foreign DNA, it is possible that self-DNA contributes to ligand-dependent cGAS activation in the context of viral infection." (PMID 31808743, 2019). "To further determine whether the resistance to viral infection by KDM5 inhibition was also dependent on cGAS-STING-TBK1-IRF3 signaling, we infected inhibitor-treated knockout cells with VSV-GFP or vaccinia virus." (PMID 30080846, 2018). "Taken together, these results suggest that ZCCHC3 targets cGAS after viral infection." (PMID 30135424, 2018). "Therefore, understand the detailed regulation of cGAS provide more targets for designing strategies to treat autoimmune diseases or viral infections." (PMID 29760876, 2018). "Without virus infection, cGAS undergoes K48-linked ubiquitination at K414, leading to p62-dependent selective autophagic degradation of cGAS." (PMID 29546673, 2018). "Collectively, these results indicate that mitochondrial alteration or damage upon DENV infection releases mtDNA into the cytoplasm of infected cells that may contribute to the activation of cGAS signaling in response to +ssRNA virus infection." (PMID 28620207, 2017). "Recent studies indicated that during viral infection the cyclic GMP/AMP synthase (cGAS) senses cytosolic DNA and catalyzes formation of the cyclic di-nucleotide cGAMP, which triggers stimulator of interferon genes (STING) and thus induces antiviral type I interferon (IFN-I) responses." (PMID 27058035, 2016). "We hypothesized that during viral infection, both viral DNA and host-derived DNA (released because of virus-induced cellular damage) concurrently activate the cGAS-STING pathway, triggering downstream signaling and IFN-α production via both wild-type cGAS and cGASΔN." (PMID 41156640, 2025). "Therefore, enhancing cGAS-STING pathway activation may be an effective strategy to restrain viral infection." (PMID 41158134, 2025). "Finally luciferase reporter activity in Gag-LUC infected THP-1 Dual cells was significantly reduced in the presence of STING inhibitor H151 and cGAS inhibitor RU.521, confirming cGAS/STING-dependent sensing of viral reverse transcripts during Gag-fusion virus infection." (PMID 38778414, 2024). "However, with the increase in animal phyla such as Mollusca, for example, the Pacific oyster (Crassostrea gigas or C. gigas), the involvement of cGAS/STING signaling-mediated production of primitive interferon-like protein (IFN-LP) has been observed upon viral infection as a defense mechanism." (PMID 38339107, 2024). "In addition to cancer therapy, the cGAS/STING pathway plays a vital role in viral infections." (PMID 39737190, 2024). "More interestingly, RNF26, another E3 ubiquitin ligase, competes with RNF5 by catalyzing cGAS K11‐linked polyubiquitination at K150, thereby protecting STING from degradation and maintaining rapid and effective induction of IFN‐I and proinflammatory cytokines after virus infection." (PMID 38525112, 2024). "Furthermore, stimulation of cells with ER stress-inducing pharmacologic agents, OGD, or viral infection resulted in the appearance of abundant dsDNA particles in the cytoplasm, which could serve as agonists to stimulate cGAS, and thus STING." (PMID 39100663, 2024). "Indeed, cGAS can be cleaved by apoptotic caspase-3 at position D319 during viral infection." (PMID 36769349, 2023).